NONO (non-POU domain containing octamer binding)
Diseases named in the same sentence as NONO in open-access papers (continued):
Sharing a sentence is not in itself a finding about the gene and the disease.
Fibroadenoma (1 paper, 2020). A benign tumor of the breast characterized by the presence of stromal and epithelial elements. "We detected an increase in the expression of six proteins (NUDT19, FBN1, NONO, FLNA, SCPEP1, and galactosidase alpha) in fibroadenoma." (PMID 33194682, 2020).
insulinoma (1 paper, 2020). "Moreover, MNX1 has been testified to expedite insulinoma cell proliferation via interaction with NONO protein." (PMID 32850524, 2020).
kidney cancer (1 paper, 2025). Primary or metastatic malignant neoplasm involving the kidney. "Notably, SFPQ, a close family member of NONO and PSPC1, has been identified as essential for the survival of both TFE3 fusion and non-fusion kidney cancer cells." (PMID 41027885, 2025).
liver cancer (1 paper, 2021). An epithelial or non-epithelial malignant neoplasm that arises from the liver. "Here, we found multifunction scaffold protein p54nrb/NONO exerted pleiotropic effects to regulate hypoxia transcription signals, thereby enhancing the progression of liver cancer." (PMID 34079086, 2021).
mucoepidermoid carcinoma (1 paper, 2018). A carcinoma morphologically characterized the presence of cuboidal mucous cells, goblet-like mucous cells, squamoid cells, cystic changes, and a fibrotic stromal formation. "CRTC1–MAML2 fusion was a major oncogenic driver for mucoepidermoid carcinoma initiation and maintenance, CRTC1–MAML2 fusion remarkably up-regulated LINC00473 transcription to promote the binding to a cAMP signaling pathway component NONO and subsequently activate CREB-mediated transcription." (PMID 30126852, 2018).
papillary renal cell carcinoma (1 paper, 2022). A rare subtype of renal cell carcinoma, arising from the renal tubular epithelium and showing a papillary growth pattern, which typically manifests with hematuria, flank pain, palpable abdominal mass or nonspecific symptoms, such as fatigue, weight loss or fever. "After their discovery in papillary renal cell carcinoma (PRCC) as PRCC-TFE3 gene fusion, further partnerships have been reported, including NONO, SFPQ, and DVL2 genes in papillary renal cell carcinomas and PEComas." (PMID 35225876, 2022).
SARS-CoV-2 (1 paper, 2022). "Several mRNA binding proteins, including Heterogeneous nuclear ribonucleoproteins (HNRNPs), dead box RNA helicases (DDX), and NONO, were activated during the innate immune response to SARS-CoV-2 infection." (PMID 35236909, 2022).
schizophrenia (1 paper, 2018). A major psychotic disorder characterized by abnormalities in the perception or expression of reality. "The SLC25A5, NONO, LMNA and RPS3A proteins were not chosen for validation because little information about the relation between schizophrenia and these proteins is available." (PMID 29514709, 2018).
Sepsis (1 paper, 2025). Sepsis is defined as life-threatening organ dysfunction caused by a dysregulated host response to infection. "Using our new plasma data (11 septic shock samples and 21 sepsis samples), the combinations of five genes (NONO, CKAP4, FCAR, PLEKHO1, BMP6) reached an overall accuracy of 93.75%, with a sensitivity of 81.82% and a specificity of 100.00%." (PMID 40665987, 2025).
cancer (26 papers, 2011 to 2025). A tumor composed of atypical neoplastic, often pleomorphic cells that invade other tissues. "NONO is a nuclear RNA–binding protein implicated in transcriptional regulation and DNA repair, with emerging but context-dependent roles in cancer progression." (PMID 41321310, 2025). "NONO is a multifunctional protein implicated in multiple physiological and pathological processes, including DNA damage repair, metabolism, cancer progression, and chemoresistance." (PMID 35803902, 2022). "Furthermore, NONO is implicated in activating Akt/MAPK/β-catenin signaling pathways which are well known to play critical roles in cancer progression." (PMID 37370134, 2023). "Long ago, a dimeric complex of NonO:SFPQ was shown to be more highly proliferative in cancer cell lines than in normal cells." (PMID 38248868, 2024). "According to our results, the cancer cell growth inhibition is due to the deregulation of apoptosis induction and to the inhibition in the expression of the gene NonO." (PMID 24101161, 2013). "Given the involvement of NONO protein modulation in the regulation of replication stress and R-loops at telomeres, we investigated whether the NONO protein can modulate the immune response pathway as a potential new therapeutic target for cancer treatment." (PMID 40943463, 2025). "We observed CPNE7 and NONO were colocalized in the nucleus of cancer cells, implying they may jointly regulate the transcription of ZFP42." (PMID 39695095, 2024). "STAT3 and NONO have been shown to facilitate cancer cell growth, invasion, and migration." (PMID 32724453, 2020). "Further studies are necessary to verify whether NonO has an active role in cancer cell proliferation." (PMID 24101161, 2013). "A small number of hypoxia-associated genes (APLN, HIF1A, and BNIP3), cancer stem cell (CSC) markers (CD24 and CD44), hormonal regulation (HR) genes (ESR1, PGR, and TFF1), other selected genes (PPARGC1A, ILK), and HKGs (RPL32, GUSB, TBP, OAZ1 and NONO) were also included in the panel." (PMID 34206049, 2021). "NONO (also named p54nrb) may also be implicated in cancer because of its roles in many biological processes, including RNA splicing, DNA repairing, and gene transcription." (PMID 27259250, 2016). "Hence, modulation of NR4A1 and NR4A2 expression by Rasd1 and NonO could have a major impact on the circadian control, and disruption of this process can give rise to metabolic diseases and cancer development." (PMID 21915321, 2011). "In this review, we focus on several other established roles of NonO and SFPQ, including their participation in the cell cycle, nonhomologous end-joining (NHEJ), homologous recombination (HR), telomere stability, childhood birth defects and cancer." (PMID 38248868, 2024). "In normal non-cancer fibroblast, the simvastatin did not inhibit the NonO gene expression, in fact, its expression did not changed in simvastatin-treated NIH-3T3 cells." (PMID 24101161, 2013). "Such a model supports the growing body of evidence of NonO and possibly SFPQ upregulation in different cancer cell types and clinical samples, suggesting that NonO might represent a potential therapeutic target." (PMID 38248868, 2024). "RBMX (RNA Binding Motif Protein X-Linked), NONO (Non-POU Domain Containing Octamer Binding) and FUS (FUS RNA Binding Protein) are the three RNA-binding proteins that have been demonstrated to be potential cancer drivers." (PMID 33202812, 2020). "The concerted expression of genes involved in different mechanisms of cell protection, like p54nrb and NonO may contribute to the survival, promoting response counteracting the apoptosis in cancer cells." (PMID 24101161, 2013). "The concerted expression of genes involved in different mechanisms of cell protection, like the human p54nrb and the murine NonO may contribute to survival, promoting response counteracting the apoptosis in cancer cells." (PMID 24101161, 2013).
cancer (continued). "The Non-POU Domain-containing Octamer Binding Protein (Nono) – also known as p54nrb in humans and NonA in fruit flies – belongs to the Drosophila Behavior Human Splicing family of proteins (DBHS) and has been implicated in the circadian clock metabolism, brain function, and cancer." (PMID 40352720, 2025). "Immunohistochemical staining indicated that nuclear and cytoplasmic expression of NONO, ERG, and Ets-1 was obviously detected in cancer cells, while their negative or weak expression was noted in normal and precancerous gastric mucosa." (PMID 29773901, 2018).
tumor (15 papers, 2012 to 2026). "Experiments have underscored that the NONO protein is integral to DNA repair and radioresistance in tumor cells." (PMID 38383403, 2024). "Finally, these genes were overlapped with the upregulated DEGs from the two GSE9782 datasets, resulting in 7 tumor stemness-related genes, including NONO, CBX3, SLC25A3, PTPRG, NPM1, HINT1, HNRNPA1." (PMID 41050668, 2025). "In addition, during the DDR process induced by tumor radiotherapy, it was found that the overexpression of the NONO protein can lead to the formation of heterodimers with SFPQ that undergo LLPS." (PMID 38383403, 2024). "Thus, even if EGFR was overexpressed with NONO knockout, tumor phenotype was partly restored." (PMID 35013116, 2022). "By integrating bulk and single-cell transcriptomic data, we identify subtype-specific roles of key circadian regulators-including ALAS1, NONO, and CSNK1D-in shaping tumor metabolism, proliferation, stromal remodeling, and immune suppression." (PMID 41898292, 2026). "In each of these contexts, the absence or malfunction of either or both NonO and SFPQ leads to either genome instability, tumor development or mental impairment." (PMID 38248868, 2024).
infection (4 papers, 2015 to 2023). The state of being infected such as from the introduction of a foreign agent such as serum, vaccine, antigenic substance or organism. "RUVBL2, ADNP, SF3A2, CDK2, PRKDC, and NONO were particularly interesting as the increase in acetylation following SIRT2 inhibition temporally aligned with the time point of maximal interaction with SIRT2 during infection." (PMID 37916830, 2023). "One of the most overexpressed protein in response to Delta-24-RGD infection is the Non-POU domain-containing octamer-binding protein (NONO)." (PMID 30123426, 2018). "Non-POU domain-containing octamer-binding protein (NONO), identified as interacting with poliovirus RNA through thiouracil cross-linking mass spectrometry, also impacts the generation of positive-sense RNA during infection." (PMID 26150805, 2015).
cardiovascular diseases (1 paper, 2025). "Non-POU domain containing octamer-binding protein (NONO) is crucial in fibrosis in cardiovascular diseases, but its role in DN fibrosis remains unclear." (PMID 41163679, 2025).
NONO also shares sentences with these, for which no sentence is quoted: colon carcinoma (2 papers); lymphoma (2); renal cell carcinoma (2); adenocarcinoma (1); Astrocytoma (1); atherosclerosis (1); bacterial infection (1); Barth syndrome (1); cervix adenocarcinoma (1); cervix carcinoma (1); chronic myeloid leukemia (1); clear cell renal cell carcinoma (1); Coffin-Lowry syndrome (1); colorectal tumors (1); Cornelia de Lange syndrome (1); Danon disease (1); Dementia with Lewy Bodies (1); Flavivirus Infections (1); frontotemporal dementia (1); Holt-Oram syndrome (1); inflammation (1); LEOPARD syndrome (1); liposarcoma (1); lumbago (1); lung carcinoma (1); metabolic disease (1); metastatic melanoma (1); metastatic prostate carcinoma (1); microcephaly (1); neuroendocrine tumors (1).
A further 9 diseases each share a sentence with NONO in 1 paper.